ATM (ATM serine/threonine kinase)
Diseases named in the same sentence as ATM in open-access papers (continued):
Sharing a sentence is not in itself a finding about the gene and the disease.
Ataxia (continued). "In mice, the ATM deficiency usually results in a shortened survival of haematopoietic cells, early frequent occurrence of lymphomas, and a lifespan over a few months only, so the manifestation of ataxia and cerebellar atrophy is usually prevented by an untimely death due to the immune deficit." (PMID 37830614, 2023). "Finally, pinpointing where, when, and how ATM deficiency causes cerebellar pathology and ataxia has been a challenge, as prior ATM-deficient mice generally lack the characteristic features needed to causally link cellular and molecular deficits to the ataxic phenotype." (PMID 34723800, 2021). "A noteworthy mutation in ATM and SETX was observed among them, and its symptoms were shown to cause ataxia in these families." (PMID 39281240, 2024). "Downregulated transcripts were found for the ATM interactome component Usp2, many non-coding RNAs, ataxia genes Itpr1, Grid2, immediate early genes and immunity factors." (PMID 37830614, 2023). "After identifying relevant changes in upstream coordinators and mechanisms of each affected pathway, it is important to explore how they are connected to ATM and how they overlap with other cerebellar ataxias." (PMID 37830614, 2023). "This possibility is enhanced by strong links of ataxias to mutations in DNA damage response pathways, including ATR and ATM and our observations that the DNA damage response regulates ZASC1:ZBTB2 interaction." (PMID 33635925, 2021). "Single patients were found to harbour mutations in ATM, SAMD9L, or FMRI that have occasionally been reported as a cause of inherited ataxia." (PMID 34600502, 2021). "As lots of ROSs are generated in the cerebellum, the response of ATM to ROSs is expected to be related to the cerebellar ataxia in AT syndrome." (PMID 30057676, 2018). "Ataxia telangiectasia fibroblasts lack G1 and G2 phase checkpoint functions indicating that activation of ATM to pATM is crucial for cell cycle control." (PMID 28746345, 2017). "Ataxia with oculomotor apraxia defines a group of genetically distinct recessive ataxias including ataxia-telangectasia (A-T, ATM gene), ataxia with oculomotor apraxia type 1 (AOA1, APTX gene) and type 2 (AOA2, SETX gene)." (PMID 23941260, 2013). "In this study, we performed a mutational screening of ATM, APTX, SETX in a selected cohort of twenty-two Italian patients presenting cerebellar ataxia, sensorimotor axonal neuropathy, and elevated AFP." (PMID 23941260, 2013). "In our survey ~60% of juvenile-to-adult cases with cerebellar ataxia, sensorimotor neuropathy and increased AFP are due to mutations in the SETX gene, and a smaller percentage to APTX and ATM gene mutations." (PMID 23941260, 2013). "The reason why ATM and APTX deficiency is required to generate ataxia in mice, when loss of either is sufficient to cause ataxia in humans, remains unclear." (PMID 34723800, 2021). "Although ATM‐deficient mice do not recapitulate the profound ataxia in A‐T, researchers have shown reduced motor coordination and abnormal walking patterns compared with wild‐type mice." (PMID 33734555, 2021). "A major factor limiting our ability to define why the loss of DDR proteins, like ATM, selectively impacts the cerebellum and causes progressive ataxia is the lack of an animal model that recapitulates these neurological symptoms." (PMID 34723800, 2021). "We are considering that the lacks of these ATM-dependent cell deaths might be the one of the reasons of the cerebellar ataxia." (PMID 30057676, 2018). "Residual levels of ATM protein may explain the relatively mild ataxia phenotype in Mennonite patients." (PMID 25077176, 2014). "Moreover, HDAC2 interacts with ATM and inhibits its function leading to neuronal cell cycle reentry and degeneration in ataxia." (PMID 22582024, 2011). "Notably, other combinations of compromised DNA repair such as DNA-PKcs (DNA-dependent protein kinase, catalytic subunit) or DNA ligase IV together with ATM loss do not develop ataxia." (PMID 34910524, 2021).
Ataxia (continued). "In this study, we determined the function of ATM in nondividing cells and speculated the cause of the cerebellar ataxia." (PMID 30057676, 2018). "We have studied a mutation c.6200C>A (p.A2067D) in the ATM gene that is unique to the Mennonite populations of Canada, Mexico, Central America, Northern Germany, and Netherlands, and is usually associated with dystonia, not ataxia, in young patients." (PMID 25077176, 2014). "Nevertheless, using conditional alleles, it has been demonstrated that CNS-specific loss of Nbs1 leads to microcephaly, defects in the development of the cerebellum and ataxia, in contrast to ATM-deficient mice or hypomorphic Nbs1 alleles that do not exhibit ataxia." (PMID 23532176, 2013). "We found a typical case of AT reported by Nakayama with a compound heterozygous ATM genotype presenting with two truncating mutations, no detectable ATM protein activity in lymphoblast cell lysates, and the onset of dystonia-myoclonic jerks with ataxia, but ataxia symptoms progress slowly." (PMID 35586824, 2022). "Here, we report new disease-relevant murine models of genome instability–driven neurodegeneration involving disabled ATM and APTX that develop debilitating ataxia." (PMID 34910524, 2021). "The DDR pathways regulated by shelterin includes ATM (Ataxia Telangiectasia Mutated), ATR (Ataxia Telangiectasia and Rad3-related), Non-Homologous End Joining (NHEJ), Homologous Recombination (HR), and Alternative Lengthening of Telomeres (ALT)." (PMID 39126110, 2024). "Early ATM genetic testing should be considered for those patients with predominant dystonia, despite without accompanying ataxia or telangiectasia." (PMID 37009283, 2023). "Our results indeed demonstrate that mice deficient in ATM and APTX develop cerebellar dysfunction, atrophy, and a progressive and profound ataxia, while mice deficient in either protein alone do not." (PMID 34723800, 2021). "Like prior ATM-deficient A-T mouse models, ATM or APTX deficiency alone did not result in mice with ataxia." (PMID 34723800, 2021). "Consistent with the behavioral results, cerebellar dysfunction was found only in the AtmR35X/R35X; Aptx−/− mice that developed ataxia and not in mice with partial or full expression of ATM or APTX." (PMID 34723800, 2021). "Last, to distinguish the contribution of ATM inactivation to this phenotype, we also established Aptx−/−;Parp1−/− mutant animals, but these did not develop ataxia." (PMID 34910524, 2021). "Although NBS1 and ATM function in the same pathway, the cerebellar ataxia is not observed in NBS patients." (PMID 30057676, 2018). "The lack of classic ataxia was in line with the ATM proficiency measured in vitro in both patients’ lymphoblastoid cell lines." (PMID 29255463, 2017). "In conclusion, we suggest that patients with ataxia, neuropathy and elevated alpha-fetoprotein should be screened for SETX and ATM genes, given that an overlapping phenotype may be present among these different genetic defined entities." (PMID 23941260, 2013). "Unfortunately, neurodegeneration remains the most poorly understood aspect of A-T, as pronounced neurodegeneration and ataxia are not observed in mice lacking ATM." (PMID 23532176, 2013). "Of two ataxia without telangiectasia [A-(T)] cases, one expressed 20% and the other ~70% of the normal ATM levels." (PMID 10864201, 2000). "Although it is well known that ATM and ATR are required to maintain genomic integrity, the precise roles of ATM and ATR during brain development are not fully understood, especially related to neuropathology such as ataxia, neurodegeneration, and microcephaly observed in human patients." (PMID 28620865, 2017). "Thus, the lack of ATM-dependent cell death may be one reason why the cerebellar ataxia is observed in AT patients but not in NBS patients." (PMID 30057676, 2018).
Ataxia (continued). "Additionally, although NBS1 and MRE11 function together mainly to activate ATM and repair DSBs, only A-TLD, but not NBS, patients show ataxia, suggesting a different yet unknown function of each component of the MRN complex controlling cerebellar development or the function of Purkinje cells." (PMID 35153719, 2021).
Telangiectasia (66 papers, 2000 to 2025). Telangiectasias refer to small dilated blood vessels located near the surface of the skin or mucous membranes, measuring between 0.5 and 1 millimeter in diameter. "There is increasing evidence that the protein kinase ATM (ataxia telangiectasia mutated) plays critical roles in response to mitochondrial dysfunction independent of its DNA damage response activity." (PMID 36966227, 2023). "The high prevalence of vascular lesions in the overall cases, as well as the syndromic CIDs group, comes from the presence of telangiectasis as a rather characteristic feature in patients with ATM mutations." (PMID 37237458, 2023). "Patients with ATM variants mainly presented telangiectasis, which is a characteristic feature in these patients, and autoimmune skin disorders, including vitiligo, psoriasis, and systemic lupus erythematosus." (PMID 37237458, 2023). "The ataxia telangiectasia mutated (ATM) gene, coding a serine/threonine kinase involved in the early stages of the homologous recombination (HR) mechanism, is one of the most altered genes in GBC." (PMID 33671809, 2021). "Upon depletion of UFD1L, we found that nucleolar segregation was reduced by more than 50% after damage relative to inhibition of the DNA damage checkpoint kinase ATM (ataxia telangiectasia-mutated), which resulted in a complete block of nucleolar release." (PMID 34389719, 2021). "Alterations of the function and activity of ATM cause severe disability, poor coordination and telangiectasia, i.e., small dilated blood vessels." (PMID 34452327, 2021). "Loss-of-function of the ATM (ataxia telangiectasia mutated) shortens lifespan due to cancer and ischemic heart disease, and ATM has been reported to be a potential target for alleviating senescence through regulating lysosomal acidification." (PMID 33143308, 2020). "LPLUNC1 also regulates the NPC cell radioresponse by inhibiting VTN-induced activation of the ataxia telangiectasia mutated kinase-Chk2 (ATM-Chk2) and ataxia telangiectasia and Rad3-related kinase-Chk1 (ATR-Chk1) pathways after ionising radiation (IR)." (PMID 30886235, 2019). "The fundamental components are the phosphoinositide 3 kinase-related kinases (PIKKs), namely ataxia telangiectasia mutated (ATM), ataxia telangiectasia, and rad3-related (ATR) and DNA-dependent protein kinase (DNA-PK)." (PMID 29641431, 2018). "When a DSB happened, the histone 2A (H2A)X was rapidly phosphorylated at ser139 by PI3K- like kinase, including ATM (ataxia telangiectasia mutated)/ATR (ataxia telangiectasia and Rad3-related) and DNA-dependent protein kinase." (PMID 27449097, 2016). "The objective of the present study was to conductmolecular analysis of the ATM gene in a cohort of 24 Polish patients withataxia-telangiectasia with aim being to provide an updated mutational spectrum in Polish ATpatients." (PMID 25614872, 2014). "Ataxia Telangiectasia (AT) is one of the best known, resulting from mutations in the ATM gene which encodes the ATM protein, a protein kinase involved in meiotic recombination and cell cycle control." (PMID 20465788, 2010). "It has been estimated that approximately 1% of the general population are ataxia telangiectasia (AT) mutated (ATM) heterozygotes." (PMID 14970866, 2004). "Moreover, DNA damage-induced signalling pathways, such as the Ataxia-telangiectasia mutated (ATM) and ataxia telangiectasia and Rad3-related (ATR) pathways, can directly regulate PD-L1 expression through various mechanisms." (PMID 39044839, 2024). "This may be attributed to DNA-damage-mediated activation of the gene mutated in ataxia telangiectasia (ATM) post IR." (PMID 36014901, 2022).
Telangiectasia (continued). "Null mutations in the Atm gene that cause the loss of functional ATM, a 370 kDa protein, results in severe characteristic cerebral ataxia and dilated blood vessels present in the conjunctivae of the eyes, also known as telangiectasia." (PMID 33868575, 2021). "Next-generation sequencing revealed mutations in the ataxia telangiectasia-mutated (ATM), SWI/SNF-related matrix-associated actin-dependent regulator of chromatin subfamily b-member 1 (SMARCB1), and phosphoinositide-3-kinase regulatory subunit 1 (PIK3R1) genes." (PMID 32537438, 2020). "Here we show that phosphorylation of GSK3β on Ser389 by p38 MAPK (mitogen-activated protein kinase) is induced selectively by DSBs through ATM (ataxia telangiectasia mutated) as a unique mechanism to attenuate the activity of nuclear GSK3β and promote survival of cells undergoing DSBs." (PMID 26822034, 2016). "We also tested whether differences in the way biological entities are named affects recognition and grounding; we found that Wip1, WIP‐1, WIP1, PPM1D, and Protein phosphatase 1D as well as ATM, Atm, and ataxia telangiectasia mutated all worked as expected (bottom, green)." (PMID 29175850, 2017). "We started by characterizing the metabolic function of ATM in primary endothelial cells (HUVECs), relevant to the telangiectasia phenotype of A-T." (PMID 39281865, 2024). "Loss of ATM impacts tissues reliant on SLC family antiporters relevant to A-T phenotypes, such as endothelial cells (telangiectasia) and pancreatic α-cells (fatty liver and diabetes) with toxic glutamate accumulation." (PMID 39281865, 2024). "In this context, the main DDR orchestrators are the members of the PIKK family of kinases, namely, ATM (ataxia telangiectasia mutated), ATR (ataxia telangiectasia and Rad3-related), and DNA-PKCs." (PMID 36091172, 2022). "DNA stress is sensed via DNA damage response sensor proteins including PARP (poly ADP-ribose polymerase), ATM (ataxia telangiectasia mutated), DNA-PK (DNA protein kinase) and ATR (ataxia telangiectasia and Rad3 related)." (PMID 35822040, 2021). "These patients had elevated expression of ATM (ataxia telangiectasia mutated) and ATR (ataxia telangiectasia and Rad3-related), which are two important kinases involved in tumorigenesis." (PMID 33109073, 2020). "Because of the IgG and IgA deficiency, cellular radiosensitivity, telangiectasia, and elevated AFP, we explored the possibility of an ATM-related dysfunction." (PMID 29255463, 2017). "MCM2 and other proteins are also direct targets of ATM (ataxia telangiectasia mutated) and ATR (ataxia telangiectasia and Rad3 related) genes, which stop DNA replication and initiate repairs." (PMID 27532114, 2016). "This is due to the phosphorylation of DBC1 at Thr454 by the ATM (ataxia telangiectasia-mutated) and ATR (ataxia telangiectasia and Rad3-related) kinases, which create a second binding site for SIRT1." (PMID 24567900, 2014). "The major molecular sensors of DNA damage include ATM (ataxia telangiectasia mutated) and ATR (ataxia telangiectasia and Rad3-related)." (PMID 22957056, 2012). "Among several roles for the ATM gene to play in the regulation of the cell cycle linking it to various clinical manifestations, its role in DNA repair and angiogenesis link it to cancer and telangiectasia formation, respectively." (PMID 40995169, 2025). "This patient with early childhood-onset ataxic neuropathy (without telangiectasia) had a homozygous likely pathogenic ATM p.Thr1743Ile variant." (PMID 37712079, 2023). "In the ATR-CHEK1 pathway, it has been reported that the activity and expression of ataxia telangiectasia (AT) cells, which do not have a functional ATM protein, are higher than normal cells." (PMID 37895364, 2023). "In humans, missense, frameshift, or nonsense mutations in the ATM gene result in the absence of a functional ATM protein and the insurgence of a rare genetic disease defined asAtaxia telangiectasia." (PMID 33665191, 2021).
Telangiectasia (continued). "ATM belongs to the phosphatidylinositol 3-kinase-like protein kinases (PIKK) family, which includes ATR (ataxia telangiectasia and RAD53 related) and DNA-PKCS (catalytic subunit of the DNA-dependent protein kinase), which all participate in DNA damage signaling." (PMID 24651490, 2014).